RN7SL577P (RNA, 7SL, cytoplasmic 577, pseudogene)
Gene: Miscellaneous RNA gene on chromosome 15 (49,042,341 to 49,042,643, reverse strand). Ensembl gene ENSG00000265942.
Homologues: Orthologues: chimpanzee Metazoa_SRP (98% identical), macaque Metazoa_SRP (92% identical). Paralogues in human: RN7SL1 (81% identical), RN7SL2 (81% identical), RN7SL126P (80% identical), RN7SL3 (80% identical), RN7SL45P (80% identical), RN7SL113P (79% identical), Metazoa_SRP (79% identical), RN7SL612P (79% identical), RN7SL627P (79% identical), RN7SL709P (79% identical), Metazoa_SRP (78% identical), RN7SL187P (78% identical), and 703 more.